ENSG00000212608
Synonyms: LOC124900563
Gene: Small nucleolar RNA gene on chromosome 3 (53,387,713 to 53,387,836, reverse strand). Ensembl gene ENSG00000212608.
Gene Ontology:
Biological process: RNA processing
Cellular component: nucleolus
Homologues: Paralogues in human: SNORA26 (77% identical).